TRPM2 (transient receptor potential cation channel subfamily M member 2)
Diseases named in the same sentence as TRPM2 in open-access papers (continued):
Sharing a sentence is not in itself a finding about the gene and the disease.
breast carcinoma (25 papers, 2012 to 2026). "TRPM2 is predominantly localized in the nuclear compartment of breast cancer cells, with approximately 40%–45% of TRPM2 residing within the nucleus and the remainder distributed among other subcellular portions such as the cytoplasm." (PMID 40078961, 2025). "We also evaluate ZGE's ability to inhibit TRPM2‐mediated calcium signaling, thereby disrupting survival and anti‐apoptotic pathways in breast cancer cells." (PMID 41306344, 2025). "It has been also shown that TRPM2 has a protective role in breast cancer cells as it facilitates the integrity of genomic DNA by helping to minimize DNA damage." (PMID 38255793, 2024). "Unlike typical ion channel functions in the plasma membrane, TRPM2 has a novel performance in the nuclear of human breast cancer cells, where it protects genomic DNA integrity." (PMID 39633507, 2024). "For instance, in case of breast cancer, the expression of the TRPM2 channel is higher in both invasive and non-invasive tumors than in normal tissues." (PMID 38255793, 2024). "More importantly, Inhibiting TRPM2 can significantly enhance the cytotoxic effects of chemotherapy drugs in triple-negative (TN) and estrogen receptor-positive (ER+) breast cancer." (PMID 39633507, 2024). "Low-level expression of TRPM2 on the breast cancer cells impeded the neutrophil cytotoxic effects and promoted lung metastasis." (PMID 36066649, 2023). "There was little research in the literature that has explored the chemotherapeutic effects resulting from TRPM2 inhibition or RNAi silencing in breast cancer cells." (PMID 37755210, 2023). "In breast cancer, inhibition of TRPM2 increased cell death after doxorubicin and tamoxifen, another commonly used chemotherapeutic agent in breast cancer therapy." (PMID 37576339, 2023). "H2O2 within the TME also acts as a cue determining tumor cell susceptibility to the cytotoxic actions of neutrophils because the neutrophil-secreted H2O2 induces the lethal influx of Ca2 + into breast cancer cells via the H2O2-activated TRPM2." (PMID 36066649, 2023). "Within this review, we will assess the existing understanding of how five specific TRP channels (TRPA1, TRPC5, TRPV1, TRPV2, and TRPM2) contribute to the resistance of breast cancer to therapeutic interventions." (PMID 37755210, 2023). "TRPM2 is highly expressed in many cancers, such as breast cancer, prostate cancer, and pancreatic cancer." (PMID 37762313, 2023). "The members of TRPM ion channel family such as TRPM2, TRPM7 and TRPM8 play vital roles in the growth, survival and metastasis of breast cancer cells, while somatic mutations affecting TRPM6 occur in breast cancer patients." (PMID 32484822, 2020). "According to the researchers, TRPM2 is a promising biomarker of aggressiveness for breast cancer, and a potential target for new therapies." (PMID 32423430, 2020). "TRPM2 has been well-recognized to promote cell death and tissue injury, however, improve the cell viability in breast cancer cell lines." (PMID 32211326, 2020). "Potential TRPM2 involvement was confirmed in cell proliferation, facilitation of cell survival, prostate cancer, melanoma, genomic stability of breast cancer cells, promotion, survival and metastases in the head and neck." (PMID 32423430, 2020). "Targeting the TRPM2 channel also promoted cell death in T cell leukemia, gastric cancer, and triple-negative and estrogen-receptor positive breast cancer cell lines." (PMID 30020827, 2018). "We previously demonstrated a unique protective role for the transient receptor potential, melastatin-2 (TRPM2) cation channel in breast cancer cells." (PMID 26178079, 2015). "It is possible that the effects of TRPM2 inhibition on genomic DNA damage in breast cancer cells are partially due to effects on the mitochondria." (PMID 25760245, 2015). "Future studies will also be required to characterize and identify the cellular effects of TRPM2 in breast cancer cells." (PMID 26178079, 2015).
breast carcinoma (continued). "Additional therapeutic insight gained from these results is that TRPM2 inhibition has the potential to eradicate breast cancer cells that are resistant to chemotherapy due to their evasion of apoptosis." (PMID 26178079, 2015). "An emerging target for the improved treatment of breast cancer is the transient receptor potential, melastatin-2 (TRPM2) channel." (PMID 26178079, 2015). "This is expected to provide a basis for inhibiting TRPM2 for the improved treatment of breast cancer, which potentially includes treating breast tumors that are resistant to chemotherapy due to their evasion of apoptosis." (PMID 26178079, 2015). "Further, it is potentially consistent with our studies that show a protective role for TRPM2 in breast cancer cells." (PMID 25760245, 2015). "We presented new data that further demonstrates the therapeutic potential of inhibiting TRPM2 function in the treatment of breast cancer." (PMID 26178079, 2015). "The present study found that TRPM2 inhibition enhanced the cytotoxicity of chemotherapeutic agents currently utilized to treat TN and ER+ breast cancer." (PMID 26178079, 2015). "This study provides insight into the role of TRPM2 in breast cancer cells that potentially provides a foundation for investigating TRPM2 inhibition to selectively target the DNA of breast adenocarcinoma cells in the future." (PMID 25760245, 2015). "In addition, in this review, it was proven that TRPM2 inhibition or the knock out enhances sensitivity to chemotherapy in breast cancer cells and thus increases cell death." (PMID 37755210, 2023). "We show here minimal effects of TRPM2 inhibition on calcium influx in breast cancer cells." (PMID 25760245, 2015). "Further, the abundance of TRPM2 protein levels in breast cancer cells may be significantly decreased as compare to their levels in neurons and developmental cells, where TRPM2-mediated calcium influx is robust." (PMID 25760245, 2015). "It is therefore possible that TRPM2 inhibition could provide the same effects in breast cancer cells that are refractive to chemotherapy, particularly those that evade apoptotic cell death, and thus survive after chemotherapy." (PMID 26178079, 2015). "Thus, the present study provides compelling evidence that TRPM2 is a novel target that can lead to improved outcomes in the treatment of breast cancer patients in the future." (PMID 26178079, 2015). "In this study, our objective was to investigate TRPM2 in two lines of human breast adenocarcinoma cells in order to analyze its function in breast cancer cells and to provide a preliminary evaluation of its potential as a pharmacologic target in breast cancer." (PMID 25760245, 2015). "In summary, we report here a novel effect promoted by TRPM2, where it functions to minimize DNA damage and thus may have a role in the protection of genomic DNA in breast cancer cells." (PMID 25760245, 2015). "In prostate and breast cancer cells, TRPM2 appears to play a protective role." (PMID 26178079, 2015). "Future studies may also include the investigation of the ADP-ribose pyrophosphatase enzymatic activity of TRPM2 channels in breast cancer cells." (PMID 25760245, 2015). "Thus, the present study presents the possibility that targeting TRPM2 is expected to provide an additional strategy to successfully treat these molecular subtypes of breast cancer tumors." (PMID 26178079, 2015). "However, in breast cancer cells, a comprehensive understanding of the chemotherapeutic effects elicited by TRPM2 inhibition is not completely known." (PMID 26178079, 2015). "Therefore, targeted TRPM2 therapy may be a neoadjuvant treatment that can improve the treatment of breast cancer patients, including chemotherapy-resistant patients." (PMID 40078961, 2025). "Similarly, the inhibition of TRPM2 enhanced the sensitivity of breast cancer cells to DOX." (PMID 39594815, 2024).
breast carcinoma (continued). "Accordingly, these studies suggest that TRPM2 is a potential therapeutic target, where its pharmacologic inhibition may provide an innovative strategy to selectively increase DNA damage levels in breast cancer cells." (PMID 25760245, 2015). "Also, TRPM2 inhibition induced alternative pathways of cell death in these breast cancer cells." (PMID 26178079, 2015). "Thus, this present study, along with these future investigations, may provide the foundation necessary for the initial rational drug design of TRPM2 inhibitors to be used in the treatment of breast cancer." (PMID 25760245, 2015). "However, it is possible that TRPM2 may have a lesser role as an ionophore or ion channel, as TRPM2 was shown to also be localized to the cytoplasmic fraction in breast cancer cells." (PMID 25760245, 2015). "It is thus possible that TRPM2 may have different roles in cardiac cells and breast cancer cells." (PMID 25760245, 2015). "For example, TRPM8 and TRPM2 are significantly overexpressed in prostate cancer, TRPM5 in lung cancer, and TRPM2 and TRPM7 in breast cancer." (PMID 41601884, 2026). "In a murine breast cancer model, ZGE demonstrated potent antioxidant and cytotoxic activities, suppressed TRPM2‐mediated oxidative stress, and promoted apoptosis via caspase‐3 activation." (PMID 41306344, 2025). "TRPMs have also been recognized as important modulators in multiple cancers progression, from which TRPM2, TRPM7, and TRPM8 have been shown to promote breast cancer development." (PMID 32211326, 2020). "Silencing TRPM2 in MCF-7 and MDA-MB-231 breast cancer cell lines induces significantly DNA damage compared to that in MCF-10A, the widely used non-cancerous breast cells." (PMID 32211326, 2020). "The role of different TRPM members has been shown in various cancers such as prostate cancer for mostly TRPM8 and TRPM2, breast cancer for mostly TRPM2 and TRPM7, and pancreatic cancer for TRPM2/7/8 channels." (PMID 29875336, 2018). "Therefore, the ability of TRPM2 inhibition to enhance cytotoxicity in TN and ER+ breast adenocarcinoma cells suggests that targeting TRPM2 may provide improved treatment options for TN and ER+ breast cancer patients in the future." (PMID 26178079, 2015). "We next investigated the effects of RNAi silencing of TRPM2 in the MCF-7 breast adenocarcinoma cell line, which is an estrogen receptor-positive breast cancer cell line." (PMID 26178079, 2015). "For instance, the elevated expression of TRPM2 is correlated with breast, lung and prostate cancer cell survival, whereas TRPV6 overexpression has been reported in prostate cancer as well as incriminated in breast cancer metastasis." (PMID 39594815, 2024). "Since these results have not been previously reported in breast cancer cells, we thus report important findings which further identify the targeting of TRPM2 as a potential strategy to improve the chemotherapeutic treatment of breast cancer patients." (PMID 26178079, 2015). "Interestingly, calcium influx is not significantly affected when TRPM2 is inhibited in breast cancer cells, indicating TRPM2 would not regulate bone metastasis in a calcium microenvironment dependent manner." (PMID 32211326, 2020). "This suggests that TRPM2 may not primarily function as a calcium channel in human breast adenocarcinoma cells, which further suggests that the role for TRPM2 in breast cancer cells may be distinct from its role in noncancerous cells." (PMID 25760245, 2015). "Furthermore, since TRPM2 exacerbates cell death in normal cells but has a novel protective role in breast cancer cells, a complete understanding of the cell death mechanisms initiated after TRPM2 inhibition in breast cancer cells is not known." (PMID 26178079, 2015).
breast carcinoma (continued). "Because these results have not been previously reported in breast cancer cells, our studies present preliminary evidence that TRPM2 is a potential therapeutic target in breast cancer and its pharmacologic inhibition is expected to selectively target breast cancer cells." (PMID 25760245, 2015). "Indeed, our data showing that reducing TRPM2 activity is not toxic in normal cells, but is toxic in breast cancer cells, supports the new paradigm leading to new cancer drugs." (PMID 25760245, 2015). "This suggests that TRPM2 may not exclusively function as a cation channel in breast cancer cells." (PMID 25760245, 2015).
Stroke (25 papers, 2011 to 2026). Sudden impairment of blood flow to a part of the brain due to occlusion or rupture of an artery to the brain. "This feed-forward positive activation model underlies the broad role of TRPM2 in many pathophysiological conditions such as infection and inflammation, thermal sensing and regulation, pain, stroke, and neurodegenerative diseases." (PMID 41511359, 2026). "Blocking TRPV3 or TRPM2 shows potential for reducing brain damage and improving stroke outcomes, an effect potentially linked to modulation of γδ T cell activity." (PMID 40746532, 2025). "Our findings provide mechanistic insights and a proof of principle for developing new strategies targeting the bilirubin-binding pocket in TRPM2 channels to alleviate and prevent brain injury associated with stroke and jaundice in patients." (PMID 36921602, 2023). "This confirms the neuroprotective role of TRPM2 inhibition in stroke and suggests that peptide-based uncoupling of TRPM2-NMDAR association is a promising therapeutic strategy for ischemic stroke." (PMID 37576339, 2023). "Our findings also implicated the bilirubin-binding cavity in the TRPM2 channel as a potential target for developing therapeutics to alleviate ischemic injury in stroke and other HB-related neuronal injuries." (PMID 36921602, 2023). "TRPM2 deficiency or pharmacological inhibition attenuates infarct size, neuronal loss, and memory impairment after stroke induced by transient global ischemia." (PMID 30215158, 2019). "TRPC1/3/4/6, TRPV1/2/4, and TRPM2/4/7 channels have been implicated in stroke pathophysiology." (PMID 36527242, 2023). "In recent years, TRPM2 has been shown to be involved in the pathophysiology of ischemic stroke in all the aspects, including accelerating the development of upstream risk factors outside the brain and aggregating the post-stroke pathological damage inside the brain." (PMID 35159300, 2022). "TRPM2 expression is highest within the brain and recent work in our lab demonstrated that TRPM2 is expressed and functional in pyramidal neurons of the hippocampus, a subset of neurons that are particularly susceptible to oxidative stress-induced damage in stroke and neurodegenerative disease." (PMID 22487454, 2012). "Deletion of neuronal TRPM2 reduced Ca2+ overload, mitochondrial stress, and cell death, resulting in reduced brain injury in a mouse stroke model." (PMID 41511359, 2026). "Accumulating evidence including our previous studies have indicated that TRPM2 is involved in many ROS‐related diseases such as inflammation, ischemia–reperfusion injury, stroke, diabetes, pericytes injury, neurodegeneration, and depression." (PMID 40672432, 2025). "In contrast, we previously showed TRPM2 genetic depletion or pharmacologic inhibition confers acute neuroprotection in male mice after experimental stroke and GCI." (PMID 40822706, 2024). "TRPM2 has been well established as a target for stroke therapy with several structurally distinct blockers, such as clotrimazole, tatM2NX, and A23, considered neuroprotective in preclinical studies with animal models." (PMID 36921602, 2023). "The TRPC1/3/4/6, TRPV1/2/4, and TRPM2/4/7 channels have been extensively investigated focusing on their effects on neurons and gliocytes post‐stroke." (PMID 36527242, 2023). "Using an in vivo stroke model, Trpm2 knockout mice exhibit smaller infarct volume at 48 hours after tMCAO operation when compared with wild-type mice." (PMID 32963700, 2020). "Altered TRPM2 channel expression and/or function are also reported under diseased conditions such as stroke, Western Pacific amyotrophic lateral sclerosis (WP-ALS) and parkinsonism-dementia (PD)." (PMID 21291387, 2011). "After stroke occurrence, ischemic injury induces the release of endogenous bilirubin, which increases neuronal excitability and ischemic infarct volume through the regulation of the TRPM2 pathway." (PMID 38313676, 2024).
Stroke (continued). "Overall, inhibition of TRPM2 could be an effective therapeutic target for the treatment of stroke in men." (PMID 37576339, 2023). "The potential therapeutic role of TRPM2 blockade in stroke remains controversial." (PMID 36527242, 2023). "Indeed, deletion of PARP, a potent signal for TRPM2 activation, has been shown to be neuroprotective in males and deleterious in females, where stroke-mediated cell death involves caspase-dependent apoptosis." (PMID 37576339, 2023). "Bilirubin, which exerts as an direct activator for TRPM2, was most recently found to be released in the brain subjected to oxygen-glucose deprivation (OGD), and to aggravate brain damage in the stroke in a manner strongly sensitive to molecular perturbation of the bilirubin-binding site on TRPM2." (PMID 37842082, 2023). "Several TRPM channels, such as TRPM2, TRPM4, and TRPM7 have been implicated in stroke." (PMID 36527242, 2023). "Therefore, TRPM2, as a potential target for stroke therapy, needs to establish a balance between effects on microglia and neurons." (PMID 36527242, 2023). "One explanation for this sex-dependent TRPM2 effect in stroke cell death may reside in a greater sensitivity to ADPR in males and/or activation of different signaling pathways in males versus females after ischemic injury." (PMID 37576339, 2023). "Given the known roles of TRPM2 in stroke, we first explored whether this channel was the substrate underlying the heightened effects of HB on infarct volumes." (PMID 36921602, 2023). "Moreover, TRPM2 was found to be related to delayed neuron death after ischemic stroke, and TRPM2 deletion prevented post-stroke cognitive dysfunction in mice." (PMID 35159300, 2022). "Ischemic, stroke-induced TRPM2 activation leads to significantly increased extracellular zinc ions." (PMID 35055089, 2022). "In addition, it has been shown that TRPM2 contributes to ischemic brain injury after stroke, which mainly depends on its role in activating peripheral immune cells." (PMID 33455532, 2021). "It implicates neuronal TRPM2 involves in an essential mechanism in experimental stroke." (PMID 33455532, 2021). "Indeed, in a rat model of ischemia, the expression of TRPM2 mRNA increased from 1 to 4 weeks following stroke induction." (PMID 30037128, 2018). "For example, TRPM2 expression is up-regulated in microglia that parallels with microglial activation in a stroke animal model, consistent with the idea that the TRPM2 channels in microglia are involved in the CNS responses to oxidative stress and brain damage due to ischemic injury." (PMID 21291387, 2011). "The first evidence linking TRPM2 with ischemic stroke was provided by Fonfria and collaborators, who showed increased TRPM2 mRNA expression and function after ischemic injury in the microglia of the transient middle cerebral artery occlusion (tMCAO) rat stroke model." (PMID 37576339, 2023). "TRPM2 senses hydrogen peroxide but also specific nucleotides and may offer an avenue for development of new agents that suppress stress-related inflammatory disorders, adverse effects of stroke, and degenerative conditions of the nervous system and pancreas." (PMID 21291387, 2011). "Increased expression or activation of TRPM2, TRPV2, and TRPV4 was observed in stroke." (PMID 41399206, 2025). "Therefore, inhibition of TRPM2, TRPV2, and TRPV4 channels emerges as promising anti‐neuroinflammatory targets for stroke treatment." (PMID 41399206, 2025). "Using an in vivo stroke model, Alim and coworkers demonstrated a shift in the GluN2A/GluN2B ratio toward the induction of GluN2A subunits and activation of the downstream prosurvival signalling pathways Akt and ERK1/2 in TRPM2 KO mice." (PMID 37576339, 2023).